MOK (MOK protein kinase)
Description:
Able to phosphorylate several exogenous substrates and to undergo autophosphorylation. Negatively regulates cilium length in a cAMP and mTORC1 signaling-dependent manner.
Synonyms: RAGE-1; RAGE; RAGE1; STK30
Tractability: Small molecule: a high-quality ligand is known; it belongs to a druggable protein family. PROTAC: ubiquitination databases record sites on it.
Target class: Enzyme; Transferase
Gene: Protein-coding gene on chromosome 14 (102,224,500 to 102,305,190, reverse strand). Ensembl gene ENSG00000080823.
Subcellular location: Cytoplasm; Cell projection, cilium; Nucleus
Subcellular location (Human Protein Atlas): Endoplasmic reticulum; End piece; Mid piece; Principal piece
Gene Ontology:
Molecular function: protein serine/threonine kinase activity; protein serine kinase activity; ATP binding; cyclin-dependent protein serine/threonine kinase activity; protein kinase activity
Biological process: intracellular signal transduction; regulation of cell cycle
Cellular component: ciliary base; cilium; cytoplasm; nucleus
Genetic constraint (gnomAD): Loss-of-function variants: 40 observed, 40.31 expected, observed/expected ratio (o/e) 0.99, 90% interval 0.77 to 1.29. The upper end of that interval is the gene's LOEUF score, 1.29, which puts it in group 5 of 6, group 1 being the genes least tolerant of losing a copy. Missense variants: 439 observed, 463.77 expected, observed/expected ratio (o/e) 0.95, 90% interval 0.88 to 1.02. Synonymous variants: 185 observed, 187.66 expected, observed/expected ratio (o/e) 0.99, 90% interval 0.87 to 1.11.
Homologues: Orthologues: chimpanzee MOK (99% identical), macaque MOK (94% identical), rat Mok (84% identical), dog MOK (84% identical), mouse Mok (84% identical), pig MOK (78% identical), rabbit MOK (76% identical), tropical clawed frog mok (63% identical), Caenorhabditis elegans F52B5.2 (18% identical). Paralogues in human: CILK1 (35% identical), MAK (35% identical), MAPK15 (25% identical), MAPK7 (25% identical), MAPK6 (24% identical), MAPK1 (24% identical), MAPK3 (24% identical), MAPK10 (23% identical), MAPK12 (23% identical), MAPK13 (23% identical), MAPK9 (23% identical), MAPK4 (23% identical), and 7 more.
Diseases named in the same sentence as MOK in open-access papers:
MOK is named in the same sentence as 20 diseases in open-access papers, as found by Europe PMC text mining. Sharing a sentence is not in itself a finding about the gene and the disease. The quoted sentences say what the papers report.
chordoma (2 papers, 2022 to 2023). Chordomas are rare malignant tumors arising from embryonic remnants of the notochord in axial skeleton. "Knockdown of AURA, MOK and CDK9 in chordoma cell lines and treatment with CDK9 inhibitor AZD4573 were shown to compromise cell proliferation in functional experiments." (PMID 37197427, 2023). "Significant differences between chordoma and normal tissue were identified for three kinases: Aurora kinase A (AURA), Cyclin-dependent kinase 9 (CDK9) and MAPK/MAK/MRK overlapping kinase (MOK)." (PMID 37197427, 2023). "Despite the slow growth of chordoma cells, JHC7 proliferation rate after knockdown of AURA, CDK9, and MOK was nevertheless significantly suppressed relative to control cells as measured by CCK8 assay (–I)." (PMID 36248973, 2022). "Second, to evaluate the roles of AURA, CDK9, and MOK in chordoma cell proliferation, we silenced AURA, CDK9, and MOK protein expression in chordoma cell lines using siRNAs, and demonstrated that knockdown efficacy to be over 70% in JHC7 cells (–F)." (PMID 36248973, 2022).
melanoma (2 papers, 2002 to 2022). A malignant, usually aggressive tumor composed of atypical, neoplastic melanocytes. "Moreover, MOK belongs to the same MAPK superfamily, as MEK1 and MEK2 proteins, which have crucial roles in tumorigenesis and whose inhibition is currently an attractive strategy in melanomas with BRAF mutation." (PMID 35993275, 2022). "In addition, this study revealed an increase in Adenosine-to-Inosine editing in Alu regions and in non-repetitive regions, including the hyperediting of the MOK and DZIP3 genes in relapsed tumour samples during targeted therapy and of the ZBTB11 gene in NRAS mutated melanoma cells." (PMID 35993275, 2022).
adenoma (1 paper, 2023). A neoplasm arising from the epithelium. "To date, only the expression of MOK in mouse wild-type and cancerous intestinal cells has been analyzed by Western blotting, showing the downregulation of MOK in adenomas." (PMID 37568654, 2023).
ciliopathy (1 paper, 2014). A genetic disorder of the cellular cilia or the cilia anchoring structures, the basal bodies, or of ciliary function. "For example, MAK, negative regulator of cilia length and close relative of ICK and MOK, has been linked to the retina-specific ciliopathy retinitis pigmentosa." (PMID 25243405, 2014).
tumor (5 papers, 2002 to 2022). "Indeed, the MAPK/MAK/MRK overlapping kinase (MOK) mRNA was significantly more edited in tumours from patients who relapsed during targeted therapy." (PMID 35993275, 2022). "ICK protein level was significantly up-regulated whereas MOK protein level was markedly down-regulated in intestinal adenomas, suggesting a “tumor promoting” role for ICK and a “tumor suppressor” role for MOK during intestinal tumorigenesis." (PMID 24244486, 2013).
MOK also shares sentences with these, for which no sentence is quoted: renal cell carcinoma (3 papers); cancer (2); mesothelioma (2); acute myeloid leukaemia (1); cholangiocarcinoma (1); colon cancer (1); Fanconi anemia (1); head and neck cancer (1); hepatocellular carcinoma (1); intestinal cancer (1); metabolic disorders (1); neurological diseases (1); retinitis pigmentosa (1); skin cutaneous melanoma (1); theileriasis (1).